NRAS (NRAS proto-oncogene, GTPase)
Diseases named in the same sentence as NRAS in open-access papers (continued):
Sharing a sentence is not in itself a finding about the gene and the disease.
melanoma (continued). "The approach is also shown to capture differences in the immune-cell networks of BRAF versus NRAS mutated metastatic melanomas, and the dynamic changes in resistance to targeted kinase inhibitors in MAPK signalling." (PMID 27377892, 2016). "The susceptibility to Prima-1, 3-BrPA and NAC in MelJuso cells (BRAF wild-type (wt) and NRAS-Q61L mutant) was compared with that of C8161 melanoma with an enhancing KRAS G12D mutation and a G464E mutation in the BRAF P loop region." (PMID 27863474, 2016). "In the present study, we showed that ETS1 is expressed in melanoma cell lines and is constitutively phosphorylated by ERK on Thr38 in melanoma cell lines due to the activation of the MAPK pathway associated with BRAF or NRAS mutations." (PMID 27449293, 2016). "For these studies we selected BLM and A375 human melanoma cell lines, representative of the most frequent genetic mutations in melanomas (NRAS and V600E BRAF in BLM and A375 cells, respectively)." (PMID 27461002, 2016). "BRAF and NRAS mutations are the most common genetic drivers of melanoma, found in ~50% and ~20% of tumors respectively, and are nearly mutually exclusive." (PMID 27152946, 2016). "More recently, therapeutic trials reported an activity of MEK1/2 inhibitors in patients with NRAS-mutated melanoma." (PMID 26204954, 2015). "NRAS mutations occur at about 15% to 25% in melanoma patients and are known to activate the RAS–RAF–MEK–ERK pathway." (PMID 26544513, 2015). "Mutations in BRAF (at position V600) and NRAS (G12/13, Q61) are responsible for 50 and 20% of melanomas, respectively." (PMID 26424083, 2015). "First we examined ZA’s short-term (72 h) effect on melanoma cells with various NRAS, BRAF and PTEN mutation status, but the role of these mutations on treatment response was not equivocal." (PMID 25646931, 2015). "We therefore examined the impact of PLX4032 and MEKi on RHOB expression in wild type BRAF melanoma cells harboring mutations in NRAS (WM1346 and SK-MEL2 cells), KIT (WM3211 cells) or KRAS (WM1791C cells)." (PMID 26098773, 2015). "In a clinical trial with one of the MEK inhibitory drugs (MEK162) about 20% of patients with NRAS mutated melanoma showed clinical responses with a median progression free survival of 3.7 month." (PMID 25645078, 2015). "To understand the molecular mechanisms underlying the differences between NRAS and NRAS-ΔPTEN mouse melanomas and the role of PTEN in β-catenin nuclear localization, we first studied the MAPK and PI3K signalling pathways." (PMID 26307673, 2015). "The Sk-Mel-2 cell line carries an NRAS mutation, NRAS is mutated in 18% of melanomas (range, 0–50%)." (PMID 26201960, 2015). "A panel of 14 human melanoma cell lines with various NRAS mutations was used for this study to investigate the growth inhibitory effect of this combination." (PMID 25645078, 2015). "The main NRAS-mutations affect the glutamine at the amino-acid position 61, in 80–90 % of NRAS-mutant melanomas, with mutations encoded as NRASQ61R, NRASQ61L, and NRASQ61K." (PMID 26204954, 2015). "Nevertheless, the numerous NRAS mutated samples included in our study offers the opportunity to focus on performances of the new SP174 anti- NRASQ61R antibody in the melanoma mutational screening." (PMID 26204954, 2015). "Shorter survival from initial melanoma diagnosis for NRAS patients compared to WT has been reported, and NRAS mutation status has been identified as an independent predictor of shorter survival after a diagnosis of stage IV melanoma." (PMID 26305188, 2015). "As recent data suggested, new more efficient therapeutic options are becoming available in NRAS-mutated melanomas such as MEK-inhibitors and immunotherapy." (PMID 26204954, 2015). "In another study, activation of β-catenin increased metastasis in NRAS-driven melanomas, whereas mice carrying an NRAS mutation alone generated fewer tumors." (PMID 26393652, 2015).
melanoma (continued). "This analysis was carried out to assess if BRAFV600 and NRAS mutation status affects the clinical outcome of anti-CTLA-4-treated melanoma patients." (PMID 26426340, 2015). "BRAF mutation is detected in about 40 to 70% of the cases while NRAS mutation is present in 10 to 30% of melanomas." (PMID 25646931, 2015). "NRAS-mutated melanoma cell lines are sensitive to MET inhibition with regards to proliferation, migration and apoptosis." (PMID 25294187, 2015). "To confirm these results in human melanoma cells, we used two NRAS mutated melanoma cell lines which express different levels of RICTOR." (PMID 26356562, 2015). "The identification of downstream pathways affected by NRAS mutations is critical to drug development for NRAS-mutant melanomas." (PMID 25537510, 2015). "The importance of this pathway is highlighted by the finding that BRAF and NRAS mutation are the two most important oncogenic mutations in melanoma and both of these mutations result in the constitutive activation of the RAS-RAF-MEK-ERK signaling cascade." (PMID 25646931, 2015). "In our study, 29.1 % of the patients (23/79) were concluded to have a NRAS-mutated melanoma (17.7 % (14/79) NRASQ61R, 5.1 % (4/79) NRASQ61Land 6.3 % (5/79) NRASQ61K)." (PMID 26204954, 2015). "In melanoma cells, NRAS mutations have been shown to be associated with increased activation of two main downstream signaling pathways: the PI3K/Akt and the MEK/ERK cascades." (PMID 26225426, 2015). "Circulating mutant NRAS presumably originates from a subset of the melanoma burden, and this is supported by the fact that NRAS mutant ctDNA was consistently lower than the BRAF mutated ctDNA." (PMID 26524482, 2015). "Although RICTOR overexpression was not oncogenic in Melan-a, overexpression of RICTOR in transformed G12VNRAS Melan-a stimulated their clonogenicity, demonstrating that RICTOR amplification can cooperate with NRAS mutation to stimulate melanoma proliferation." (PMID 26356562, 2015). "In particular, metformin induces cell-cycle arrest in the G0/G1 cell-cycle phase and a strong inhibition of cell viability by induction of autophagy and apoptosis in different melanoma cells independently of the BRAF or NRAS mutational status." (PMID 26322273, 2015). "Mutations in NRAS occur in 15–20 % of melanomas and result in constitutive activation of the NRAS protein and enhanced MAP kinase signaling." (PMID 26052356, 2015). "NRAS mutations, primarily at codon Q61, are the second most common melanoma driver event, occurring in 13-25% of melanomas." (PMID 25537510, 2015). "Altogether thirteen human melanoma cell lines with different NRAS, BRAF and PTEN mutational status were treated with the prenylation inhibitor zoledronic acid (ZA)." (PMID 25646931, 2015). "Gab2 amplification is associated with melanoma arising from sun-protected sites and often occurs independently from oncogenic NRAS or BRAF mutations or amplifications of the KIT gene." (PMID 26095858, 2015). "Similar results were obtained with another mouse melanoma model in which the NRAS mutation is NRASG12D and the activation of the mutation occurred at 10 weeks of age in melanocytes, using the CreERt2–LoxP–tamoxifen system." (PMID 26307673, 2015). "NRAS mutated patients developed LM within 5 yrs from primary melanoma with larger lesions compared with BRAF (mean diameter 3.3 ± 2.2cm vs 1.9 ± 1.1cm, p = 0.2)." (PMID 26305188, 2015). "Nevertheless, the determination of NRAS mutational status is already of interest in melanoma treatment strategies." (PMID 26204954, 2015). "NRASQ61R appears to be the more frequent NRAS mutation in melanoma with about 40–67 % to of NRAS mutations." (PMID 26204954, 2015). "The genetic lesions in melanoma, including NRAS and BRAF mutations, are well characterized, and activated BRAF kinase has been demonstrated to be an effective drug target for melanoma therapy." (PMID 25642713, 2015).
melanoma (continued). "It is also interesting to note that NRAS mutations are the second most common mutations to occur in melanomas (20%) next to BRAF mutations (50%)." (PMID 26294993, 2015). "Activating mutations in NRAS (usually at codons Q60/61 and G12/13) are detected in approximately 20% of melanomas, which can result in activation of various pathways, including the RAS/RAF/MEK/ERK, protein kinase C (PKC), and PI3K/AKT pathways." (PMID 26393652, 2015). "A further 10 to 15% of melanomas have the mutually exclusive NRAS mutation, another important driver mutation in melanoma." (PMID 24693430, 2014). "MEL9, the adrenal gland metastasis that was hypermutated, harbored mutations in both BRAF (H574L) and NRAS (Q61R); these two mutations were found to be present in the same variant allele frequency cluster (see Subclonal architecture in melanoma below)." (PMID 25393105, 2014). "In a limited validation of potentially actionable low frequency mutations, a NRAS G12D mutation in a melanoma was shown to be a false positive." (PMID 24885028, 2014). "In vivo, MEK inhibitors are effective in NRAS-mutated melanoma, though therapeutic activity is modest compared to BRAFi in BRAF mutant melanoma." (PMID 25142146, 2014). "In melanoma, Axl is associated with NRAS mutations compared to BRAF mutations, and is inversely correlated with the expression of the microphthalmia-associated transcription factor (MITF)." (PMID 25344858, 2014). "Genome MuSiC v0.4 is then used to investigate the presence of significantly mutated pathways, recurrent mutations, clinical correlations and mutation-relations between genes (such as mutual exclusivity of BRAF and NRAS mutations in melanoma)." (PMID 24752294, 2014). "Multiple genetic parameters have been associated with response to chemotherapy, but despite their high frequency in melanoma nothing is known about the impact of BRAF or NRAS mutations on the response to chemotherapeutic agents." (PMID 24941944, 2014). "MAPK pathway is the main hyper-activated signaling cascade in melanoma, mainly as consequence of mutations in oncogenes such as BRAF and NRAS (the latter being mutated in about 20% of melanomas)." (PMID 24920406, 2014). "Promisingly, PLX 7904 inhibited ERK1/2 phosphorylation in mutant BRAF melanoma cells with acquired resistance to vemurafenib/PLX4720 that is mediated by a secondary mutation in NRAS." (PMID 24743024, 2014). "Mutations in BRAF and NRAS (~20% of melanomas of the same origin/location as BRAF-mutated melanomas) are almost always mutually exclusive." (PMID 24743024, 2014). "The patients’ age at diagnosis of stage III melanoma was significantly lower in tumors with BRAF mutations in contrast to patients with NRAS mutations, who were on average older." (PMID 24959217, 2014). "NRAS mutations are frequent in melanoma, however many other cancer types also harbor mutant, constitutively active NRAS." (PMID 25277205, 2014). "Clinical variables in this study included tumour anatomical site, tumour thickness, tumour subtype, solar elastosis score, pigmentation scores and BRAF/NRAS mutation status (known oncogenic drivers in melanoma)." (PMID 24752294, 2014). "To address this possibility we compared expression levels of the key kinases and two major negative regulators of the pathway, SPROUTY2 and RKIP, in the GHM vs. human melanoma cell lines with activated ERK1/2 due to oncogenic BRAF or NRAS mutations." (PMID 25413220, 2014). "If the primary melanoma was a cutaneous melanoma, mutation analysis of NRAS and BRAF can be of help, but since these mutations are hotspot mutations, it is of limited use." (PMID 25593912, 2014). "CH5126766/RO5126766 induced G1 cell cycle arrest in two melanoma cell lines with the BRAF V600E or NRAS mutation." (PMID 25422890, 2014).
melanoma (continued). "Given its specificity for ERK and the potential for ERK inhibition to inhibit both MAPK and PI3K/AKT pathways, we evaluated the susceptibility of wild-type, mutant BRAF- or NRAS-melanoma, and BRAF-mutant melanoma with acquired BRAFi resistance." (PMID 25142146, 2014). "PLX4720 reduced the effect of PD0325901 in NRAS-mutated melanoma cells, whereas the RAF/MEK inhibitor CH5126766 markedly inhibited the colony formation with inhibition of the RAF-MEK pathway even in NRAS-mutated melanoma cells." (PMID 25422890, 2014). "In this study, we also confirmed the antitumor effects of CH5126766 in NRAS-mutated melanoma cells in vivo as well as in vitro, and also in KRAS-mutated cells in vitro." (PMID 25422890, 2014). "Recently, a non-randomized phase-2 study has demonstrated that MEK162 shows activity in NRAS-mutated melanoma." (PMID 24713450, 2014). "Mutations of the two oncogenes (BRAF and NRAS) have a well established and powerful predictive role as validated targets in recently developed molecular targeted therapy for melanoma." (PMID 24959217, 2014). "Activating mutations in NRAS have been reported in approximately 20% of all melanomas and are potentially sensitive to therapeutics that target downstream signaling through mitogen-activated protein kinase kinase and phosphatidylinositol 3-OH kinase or AKT." (PMID 24885028, 2014). "In a Phase II trial, treatment with MEK162 was shown to have effect in some patients with advanced NRAS-mutated melanoma and a Phase III trial is ongoing." (PMID 25593912, 2014). "Oncogenic mutations in the Neuroblastoma Rat Sarcoma oncogene (NRAS) are frequent in melanoma, but are also found in several other cancer types, such as lung cancer, neuroblastoma and colon cancer." (PMID 25277205, 2014). "PPP6C is a serine-threonine phosphatase, mutated in 12% of sun-exposed melanomas exclusively with BRAF or NRAS mutations." (PMID 24743024, 2014). "Although it has been demonstrated in experimental models that a mutation in NRAS is capable of inducing melanoma in Cdkn2a-deficient mice, NRAS mutations occur in the congenital nevi at a similar frequency to melanoma." (PMID 24959217, 2014). "We examined the activity of CH5126766/RO5126766 in a panel of malignant tumor cell lines including melanoma with a BRAF or NRAS mutation." (PMID 25422890, 2014). "The P-ERK1/2 levels were comparable to those seen in human melanoma cell lines with oncogenic BRAF or NRAS mutations, in contrast to a cell line with wild-type BRAF and NRAS." (PMID 25413220, 2014). "The driver mutations in BRAF and NRAS that have been identified cannot fully explain melanoma oncogenesis, as these same mutations have been found at similar rates in benign nevi, or moles." (PMID 25393105, 2014). "The distribution of BRAF and NRAS mutations in this cohort was similar to that in previously reported studies (particularly consistent with stage IV melanoma) with mutually exclusive BRAF-mutants found in 62% and NRAS-mutants in 17% of cases." (PMID 24959217, 2014). "The BRAF and NRAS genotype distribution in the nodal metastases of cutaneous melanomas is identical to that observed in stage IV melanoma, with BRAF p.V600E as the most frequent mutation harbored by melanoma cell metastases in lymph nodes." (PMID 24959217, 2014). "Activating mutations in the serine/threonine kinases BRAF, and NRAS were identified in 66% and 15% of melanoma cell lines, respectively, establishing MAPK signaling as a new therapeutic target in melanoma." (PMID 23340652, 2013). "Prevalence and distribution of pathogenetic mutations in BRAF and NRAS genes were evaluated in multiple melanoma lesions from patients with different geographical origin within the same Italian population." (PMID 23987572, 2013).
melanoma (continued). "Overall, a total of 749 tumor samples (451 primary melanomas and 298 melanoma metastases) was screened for BRAF mutations; among them, available DNA from 528 specimens (312 primary melanomas and 216 melanoma metastases) was analyzed for mutations in NRAS gene." (PMID 23987572, 2013). "It is interesting to note that in the majority of melanomas with mutations in BRAF or NRAS, the expression of c-KIT seems reduced to allow tumor progression." (PMID 24416617, 2013). "RAS molecules, comprising HRAS, KRAS, and NRAS, are small GTPases or G proteins, and activating mutations in NRAS are found in 10%–20% of melanomas." (PMID 23634303, 2013). "Most common melanoma mutations are in NRAS (15–30% of the cases), among which the most frequent are substitutions of glutamine at position 61 by a lysine or an arginine (Q61K, Q61R)." (PMID 24416617, 2013). "At the RNA level, there was good positive correlation between levels of CDK2 and the transcription factor MITF in both BRAF-V600E and NRAS mutated melanoma cell lines." (PMID 23527225, 2013). "The NRAS and BRAF genes are frequently mutated in melanoma, suggesting that the NRAS-BRAF-MEK-ERK signaling pathway is an important target for therapy." (PMID 23658559, 2013). "Previous work has demonstrated that forced expression of a non-degradable phosphorylation mutant of CTNNB1 can increase the metastatic potential of melanoma cells harboring activating mutations in the NRAS/phosphatidylinositol 3-kinase pathways." (PMID 24114839, 2013). "Activating mutations in two of MAPK upstream regulators, BRAF and NRAS is seen in up to 80% of melanomas and also correlates with melanoma aggressiveness and poor prognosis." (PMID 23935925, 2013). "The ability of dinaciclib to induce apoptosis in the melanoma cell line panel was unrelated to either CDK2 expression levels or BRAF/NRAS mutational status, suggesting that this drug had broad-spectrum anti-melanoma activity." (PMID 23527225, 2013). "NRAS-mutations within Exon 2 were found in 11.9% (n=5), 18.2% (n=8) and 14.3% (n=3) of melanomas, associated nevi and control nevi, respectively." (PMID 23861977, 2013). "Whereas KRAS mutations are frequent in colorectal cancer, lung cancer and pancreatic cancer, NRAS mutations are by far the predominant alteration among RAS isoforms in melanoma." (PMID 23660168, 2013). "The aim of this study was to evaluate prevalence and distribution of pathogenetic mutations in BRAF and NRAS genes among melanoma patients with different geographical origin within the same Italian population." (PMID 23987572, 2013). "Mutations in BRAF gene were detected in 223/451 (49%) primary melanomas and 153/298 (51%) metastatic tissues, whereas NRAS mutations were found in 46/312 (15%) primary tumors and 34/216 (16%) melanoma metastases." (PMID 23987572, 2013). "The aim of this study was to evaluate the predictive and prognostic impact of genetic disturbances and expression levels of BRAF together with NRAS mutations in patients treated with DTIC monotherapy for advanced melanomas." (PMID 23673558, 2013). "Targeting this pathway with MEK inhibitors showed activity for patients with melanoma presenting with NRAS mutations." (PMID 23895135, 2013). "RNA (siRNA)-mediated depletion of NRAS in two melanoma cell lines (224 and BL, which harbor a Q61R NRAS mutation) inhibits proliferation and renders cells more sensitive to chemotherapy." (PMID 23515890, 2013). "Melanomas with NRAS mutations are more likely to be thicker tumors and to have a higher mitotic rate." (PMID 27429256, 2013).